S1PR4 (sphingosine-1-phosphate receptor 4)
Diseases named in the same sentence as S1PR4 in open-access papers (continued):
Sharing a sentence is not in itself a finding about the gene and the disease.
tumor (23 papers, 2012 to 2025). "These in vitro studies suggested a tumor-promoting role for S1PR4 by shifting tumor-associated inflammation towards an anti-inflammatory pattern." (PMID 35163211, 2022). "S1PR4 deficiency leads to a decrease in breast cancer metastasis to lung and suppression of tumor growth accompanied by reduction in suppressive immune cells and increased number of tumoricidal lymphocytes, namely cytotoxic CD8+ T-cells." (PMID 32456134, 2020). "Activation of S1PR4 signaling on human and murine tumor-associated macrophages (TAMs) by apoptotic tumor cell-derived S1P leads to the production of tumor-promoting cytokines, including IL-6 and IL-10." (PMID 28848247, 2017). "In a slightly different perspective, S1PR4 knockout in mice has been found to be beneficial in a cancer setting since it limited tumor progression through the accumulation of tumor-suppressive CD8+ T lymphocytes." (PMID 40342995, 2025). "A recent study reported that ablation of the immune cell-specific G protein-coupled receptor S1PR4 induced CD8+ T cell expansion to inhibit tumor growth and enhance chemotherapy efficacy." (PMID 38925650, 2024). "Yet, in other study, S1PR4 inhibition restrained tumor development accompanied with ameliorative chemotherapy." (PMID 37988195, 2023). "Rather, S1PR4 plays a role in immune cell activation, particularly in the activation of myeloid cells in a tumor context." (PMID 35163211, 2022). "We demonstrated herein that the expression of SGPP1, PLPP3, and S1P receptors, particularly S1PR4, positively correlates with tumor-infiltrating DCs in TNBC." (PMID 34235182, 2021). "As for S1PR4, a clinical study has shown that higher tumor expressions of SPHK1 and S1PR4 are associated with shorter disease-free survival and more advanced lymph node status in ER-negative breast cancer patients." (PMID 34820423, 2021). "Depletion of S1PR4 potentiated the effect of anti-PD-1 immunotherapy in a synergistic manner resulting in reduced tumor growth and increased survival rate of tumor-bearing S1PR4-/- compared to WT mice." (PMID 32456134, 2020). "In vitro studies demonstrated that S1P produced by apoptotic tumor cells triggered S1PR4-dependent production of IL-27 by human DCs." (PMID 28848247, 2017). "Additionally, recent data have suggested that targeting S1PRs in a more specific manner, such as S1PR2 and S1PR4 blockade, displayed an anti-tumoral effect or limited chemotherapy resistance in other tumor indications." (PMID 37760448, 2023). "Moreover, the analysis of the LGG cohort demonstrated a similar profile to S1PR1, S1PR2, S1PR3, and S1PR4, which are upregulated in tumor tissue, significantly so for S1PR2 and S1PR3." (PMID 37760448, 2023). "In the present study, based on immunohistochemical experiments, we verified the differences in the expression levels of FKBP10 and S1PR4 in different differentiation states and different tumor stages, further demonstrating the plausibility of the results of this study." (PMID 36341424, 2022). "However, more studies are required to clarify the involvement of myeloid cells in S1PR4-dependent establishment of tumor-supporting inflammation." (PMID 35163211, 2022). "Irrespective of these remaining questions, the picture emerges that targeting individual sphingosine kinases or selected S1P receptors such as S1PR4 or S1PR5 may have the highest potential in unleashing the power of the anti-tumor immune response." (PMID 35163211, 2022). "Indeed, we recently described that blocking S1PR4 signaling improved chemotherapy response and prevented tumor relapse in the PyMT model." (PMID 33014872, 2020). "Elucidating the role of S1PR4 during tumor development therefore appears promising." (PMID 28848247, 2017). "Sphingosine 1-phosphate receptor 4 expression was successfully assessed in all tumours analysed." (PMID 22460268, 2012).
tumor (continued). "For example, FTY720, an S1P modulator that binds to S1PR1, S1PR3, S1PR4, and S1PR5, has been shown to inhibit tumor growth and aggressiveness in various cancer models." (PMID 37744269, 2023). "However, due to the prominent expression of S1PR4 on lymphocytes compared to other cells, these data likely do not reflect a functional role of S1PR4, but rather indicate that S1PR4 expression in human tumors can be taken as a marker for tumor-infiltrating lymphocytes." (PMID 35163211, 2022). "For instance, FTY720, an S1P agonist that binds to S1PR1, S1PR3, S1PR4, and S1PR5, has been indicated to suppress the growth and aggressiveness of tumor in several cancer models." (PMID 31807117, 2019). "In breast cancer, S1P/S1PR4 signaling can activate the Erk1/2 and human epidermal growth factor receptor-2 (HER2) pathways and increase tumor aggressiveness." (PMID 31807117, 2019). "This led to the further finding that SphK2/S1PR4 prevented nuclear translocation of S1PR2, which in turn, prevented tumor growth, providing support for sub-cellular distribution of S1PR2, which is important for oncogenic suppression." (PMID 28415564, 2017). "According to the expression levels and regression coefficients, the downregulated BAX, PWP2, SERTAD1, S1PR4, ZFAND1, NUDT13 and ZNF107 with HR < 1 were considered as tumor suppressors, whereas the MVD, BAD, CPNE7, CPNE7, UTP23 and ZNF124 upregulated with HR > 1 were regarded as oncogenes." (PMID 36685828, 2022). "Fingolimod, an agonist of four S1PRs (including S1PR1, S1PR3, S1PR4, and S1PR5), induces receptor internalization and exerts antagonistic effects, which could markedly reduce the tumor load and abrogate the NF-κB/IL-6/STAT3/S1PR1 cascade." (PMID 34831211, 2021). "In ER negative breast cancer high tumor levels of S1PR4 and SphK1 are associated with poor patient prognosis, and in HER2+ cells S1PR4/HER2+ signaling is associated with metastasis." (PMID 28415564, 2017). "Lack of TH17 cells may have contributed to reduced tumor growth in the AOM/DSS model of CAC when S1PR4 was absent." (PMID 35163211, 2022).
cancer (7 papers, 2012 to 2023). A tumor composed of atypical neoplastic, often pleomorphic cells that invade other tissues. "Results from this study lend support to the conclusion that targeting S1PR4 could prove as an efficient strategy to restore anticancer immunity and improve cancer cell response to immunotherapy." (PMID 32456134, 2020). "In the context of cancer and with a focus on immunity, S1PR4 may represent an interesting drug target since it is mainly expressed on immune cells including macrophages and T cells, and does not affect T cell trafficking similar to S1PR1." (PMID 31379883, 2019). "Together, the studies summarized in this paragraph strongly suggest an immunomodulatory role for the immune cell-specific S1PR4 during inflammation and a potential protumoral role during cancer progression, both by modulating T cell function through myeloid cell activation." (PMID 28848247, 2017). "In addition, S1PR4 and S1PR5 play important roles in inflammation, which is also closely related to the progression of some cancers, such as colon cancer." (PMID 31807117, 2019). "S1PR4 is exclusively found in hematopoietic tissues under basal conditions, whereas S1PR5 expression is restricted to natural killer (NK) cells, dendritic cells (DCs), the central nervous system, endothelial cells, and certain cancer cells, indicating specialized functions of these two S1PRs." (PMID 28848247, 2017). "The roles of S1PR4 and S1PR5 in cancer have not been completely elucidated." (PMID 32456134, 2020).
inflammation (1 paper, 2023). Aberrant reaction of the microcirculation characterized by movement of fluid and leukocytes from the blood into extravascular tissues. "We demonstrated that S1PR4 was mainly expressed in macrophages while it exhibited lower expression both in patients and experimental mice with neutrophilic airway inflammation." (PMID 37056936, 2023). "Our experiments were on a C57BL/6 background and results showed that S1pr4-KO as well as S1PR4 agonist CYM50308 had limited role on OVA/Alum-induced eosinophilic airway inflammation." (PMID 37056936, 2023). "S1PR4, a vital receptor of bioactive sphingosine metabolites and mainly expressed in macrophages, exhibited lower expression both in patients and experimental mice with neutrophilic airway inflammation." (PMID 37056936, 2023).
S1PR4 also shares sentences with these, for which no sentence is quoted: breast tumor (2 papers); Cerebral ischemia (2); Hypertension (2); infection (2); inflammatory bowel disease (2); Allergy (1); alopecia areata (1); bacterial infection (1); brain injury (1); cardiac hypertrophy (1); COVID-19 (1); diabetes (1); eosinophilic esophagitis (1); gastric tumors (1); HIV-1 infection (1); ischemic stroke (1); kidney cancer (1); large cell lymphoma (1); lung fibrosis (1); melanoma (1); pancreatic tumor (1); parasite infection (1); pneumonia (1); Psoriasiform dermatitis (1); pterygium (1); rheumatoid arthritis (1); Stroke (1); Thrombocytopenia (1); triple-negative breast carcinoma (1); type 2 diabetes mellitus (1).
A further 2 diseases each share a sentence with S1PR4 in 1 paper.